SEMA3A (semaphorin 3A)
Diseases named in the same sentence as SEMA3A in open-access papers (continued):
Sharing a sentence is not in itself a finding about the gene and the disease.
COVID-19 (2 papers, 2022 to 2023). A disease caused by infection with severe acute respiratory syndrome coronavirus 2. "In contrast, patients with COVID-19 had significantly lower SEMA3A concentrations (14 ng/mL, IQR 11–16 vs. 21 ng/mL, IQR 15–24, p ≤ 0.0001)." (PMID 37893159, 2023). "In conclusion, we have shown that patients with COVID-19 have different expressions of SEMA3A, SEMA3C, SEMA3F and SEMA7A than healthy controls, which correlate with disease severity and outcomes." (PMID 37893159, 2023). "Firstly, we found decreased serum concentrations of SEMA3A that further decreased with COVID-19 severity." (PMID 37893159, 2023). "SEMA3A < 15.5 ng/mL predicted COVID-19 with a sensitivity of 71% and specificity of 72% (AUC 0.79, 95%CI 0.72–0.87)." (PMID 37893159, 2023). "Concentrations of the serum semaphorins SEMA3A, SEMA3C, SEMA3F, SEMA4D and SEMA7A were detectable in all patients with COVID-19." (PMID 37893159, 2023). "In conclusion, we provide the first evidence that SEMA3A, SEMA3C, SEMA3F and SEMA7A can be considered as new biomarkers of COVID-19 severity." (PMID 37893159, 2023). "While SEMA3A was decreased, SEMA3C, SEMA3F and SEMA7A were increased in COVID-19." (PMID 37893159, 2023). "Furthermore, we showed an association of semaphorin levels with COVID-19 severity; SEMA3F and SEMA7A were higher in critical COVID-19, while SEMA3A and SEMA3C negatively correlated with COVID-19 severity and were lower in the critical group." (PMID 37893159, 2023). "Furthermore, SEMA3A and SEMA3C decreased with COVID-19 severity, while SEMA3F and SEMA7A increased." (PMID 37893159, 2023).
demyelination (2 papers, 2013 to 2014). "Correspondingly, administration of Sema3A ten days after a demyelination lesion in the adult CNS influenced OPCs and remyelination." (PMID 25386118, 2014). "Administration of exogenous Sema3A did not affect the phagocytic efficiency and amount of macrophages after a demyelination lesion." (PMID 25386118, 2014).
dermatitis (2 papers, 2021 to 2022). An inflammatory process affecting the skin. "Experimentally, it has been reported that replacement of recombinant Sema3A in the lesional skin of NC/Nga mice normalized epidermal hyperinnervation, resulting in suppression of itch-related scratching behavior and improved dermatitis." (PMID 33905439, 2021). "Our previous studies have shown that Sema3A ointment inhibits epidermal hyperinnervation and scratching behavior and improves dermatitis scores in AD model mice." (PMID 33905439, 2021).
dry eye (2 papers, 2017 to 2022). "This inhibitor also maintained corneal epithelial integrity and nerve density in the dry-eye model, providing a molecular basis for targeting SEMA-3A." (PMID 36291182, 2022). "In this study, we hypothesized that inhibiting Sema3A may protect afferent nerves from damage due dry eye." (PMID 29138447, 2017). "Using a murine dry eye model, we found that topical SM-345431, a selective Sema3A inhibitor, preserved corneal sensitivity (2.3 ± 0.3 mm versus 1.4 ± 0.1 mm in vehicle control, p = 0.004) and tear volume (1.1 ± 0.1 mm versus 0.3 ± 0.1 mm in vehicle control, p < 0.001)." (PMID 29138447, 2017).
glaucoma (2 papers, 2021). Increased pressure in the eyeball due to obstruction of the outflow of aqueous humor. "We hypothesize that interfering with Sema3A signaling via inhibiting the interaction of Sema3A proteins with GAGs could be an important therapeutic goal for achieving functional recovery after CNS injuries and, in particular, as a neuroprotective approach of the retina against glaucoma." (PMID 34577606, 2021).
head and neck cancer (2 papers, 2012 to 2022). A primary or metastatic malignant neoplasm affecting the head and neck. "Because VEGF is often up-regulated in a majority of malignancies, including head neck cancer, SEMA3A signalling might be inhibited by the binding of VEGF to NRP1." (PMID 22926477, 2012). "However, the roles of SEMA3A and its receptor NRP1 have not been extensively studied, particularly in the long-term survival of patients with head and neck cancer." (PMID 22926477, 2012).
head and neck squamous cell carcinoma (2 papers, 2016 to 2021). A squamous cell carcinoma that arises from any of the following anatomic sites: lip and oral cavity, nasal cavity, paranasal sinuses, pharynx, larynx, and salivary glands. "In head and neck squamous cell carcinoma (HNSCC), SEMA3A functions to suppress tumor growth partly by accelerating HNSCC apoptosis." (PMID 34821196, 2021). "Here, we investigated the expression pattern and biological roles of SEMA3A in head and neck squamous cell carcinoma (HNSCC) by gain-of-function assays using adenovirus transfection and recombinant human SEMA3A protein." (PMID 26755661, 2016).
heart failure (2 papers, 2017 to 2023). Inability of the heart to pump blood at an adequate rate to meet tissue metabolic requirements. "Sema3A expression was upregulated in the plasma of patients with heart failure with preserved ejection fraction, and Sema3A concentrations were positively correlated with NT‐proBNP in these patients." (PMID 37310417, 2023).
Hyperglycemia (2 papers, 2020 to 2021). An increased concentration of glucose in the blood. "Following the rapamycin treatment, the upregulation of Sema3a was concomitant with an elevation in the number of small fibers, without affecting hyperglycemia in diabetic rats." (PMID 32566683, 2020).
hyperlipidemia (2 papers, 2024 to 2025). "When the relationship between hyperlipidemia, a known risk factor for acute ischemic stroke, and semaphorin levels was examined, we found that semaphorin 3A and 4A levels were positively correlated with total cholesterol and LDL levels." (PMID 41303895, 2025). "As SEMA3A has been reported to regulate actin and tubulin dynamics, and as palmitic acid alters the F-actin cytoskeleton in LSECs, we asked whether SEMA3A links hyperlipidemia to defenestration of hepatic sinusoids." (PMID 39196233, 2024).
injury (2 papers, 2011 to 2023). Damage inflicted on the body as the direct or indirect result of an external force, with or without disruption of structural continuity. "Other studies have shown that interference with Sema3A is beneficial for synaptogenesis and functional recovery following CNS trauma." (PMID 37840145, 2023). "Defining how Sema3A influences structural plasticity of the developing lung is a critical first step for determining if this pathway can be exploited to develop innovative strategies for repair after acute or chronic lung injury." (PMID 22096573, 2011). "Defining how Sema3A influences structural and functional plasticity of the developing lung is a critical first step for determining if this pathway can be exploited to develop innovative strategies for repair after acute or chronic lung injury." (PMID 22096573, 2011).
kidney damage (2 papers, 2020 to 2023). "Indeed, it was reported that SEMA3A injections in a New Zealand black (NZB)/W mice model of LN delayed the appearance of proteinuria and reduced kidney damage, as well as causing a decrease in immune complex deposition in the glomeruli, indicating the protective effect of SEMA3A in LN." (PMID 37835781, 2023). "In addition, altered serum SEMA3A levels were found to be inversely correlated with SLE disease activity, mainly with kidney damage and the presence of anti-cardiolipin antibodies." (PMID 37835781, 2023).
kidney injuries (2 papers, 2013 to 2016). "It would be interesting to speculate that a balance between the expression of the other semaphorins including Sema3A, which is pro-inflammatory, and Sema3G, which is anti-inflammatory, is important in the development of kidney injuries." (PMID 27180624, 2016).
lung adenocarcinoma (2 papers, 2022). A carcinoma that arises from the lung and is characterized by the presence of malignant glandular epithelial cells. "At the same time, the expressions of HNRNPAB/PLAUR and SEMA3A were detected in the cancer and paracancerous tissues of a lung adenocarcinoma patient, as determined by IHC." (PMID 36091160, 2022). "Furthermore, HNRNPAB/PLAUR and SEMA3A were considered by us as significant predictive target genes of the PTEN-related LINC00460/miR-150-3p axis in lung adenocarcinoma." (PMID 36091160, 2022).
meningioma (2 papers, 2012 to 2013). A generally slow growing tumor attached to the dura mater. "Nonetheless, it should be noted that Sema3A exhibits an antiangiogenic effect in meningiomas, as evident by the correlation of its high expression with reduced tumor vascularization." (PMID 23050142, 2012).
osteoarthritis (2 papers, 2018 to 2021). A noninflammatory degenerative joint disease occurring chiefly in older persons, characterized by degeneration of the articular cartilage, hypertrophy of bone at the margins and changes in the synovial membrane. "This study elucidated the role of SEMA3A in osteoarthritis and illustrated its action mechanism involving NRP-1." (PMID 34821196, 2021). "Human synovial tissues from established RA patients and patients suffering from osteoarthritis (OA) were assessed for sema3A, VEGF-A, and NP-1mRNA expression." (PMID 29670620, 2018).
Paralysis (2 papers, 2017 to 2022). Paralysis of voluntary muscles means loss of contraction due to interruption of one or more motor pathways from the brain to the muscle fibers. "Results showed that muscle paralysis led to a significant decrease in serum Sema3A levels, suggesting that Sema3A may play a mechanosensory role between muscle and bone." (PMID 35250478, 2022). "Our data may be explained by the residual repulsive activity of the mutant SEMA3A, or it may imply that SEMA3A alone is not a key component of the molecular signature affecting NMJ plasticity in ALS or BotoxA-induced paralysis." (PMID 28103314, 2017). "Using a mouse model expressing a mutant SEMA3A with diminished signaling capacity, we studied the influence of SEMA3A signaling at the NMJ with two denervation paradigms; a motor neuron disease model (the G93A-hSOD1 ALS mouse line) and an injury model (BotoxA-induced paralysis)." (PMID 28103314, 2017).
postmenopausal osteoporosis (2 papers, 2018 to 2022). Metabolic disorder associated with fractures of the femoral neck, vertebrae, and distal forearm. "Sema3A mitigates bone loss by decreasing osteoclastic bone resorption and increasing osteoblastic bone formation in an ovariectomized mouse model of postmenopausal osteoporosis, and Sema3a suppresses osteoclastogenesis and promotes osteoblastogenesis in cultured cells in vitro." (PMID 29975739, 2018). "A previous study used centrifugal force to investigate postmenopausal osteoporosis; however, our compression and tension experiment that mimicked OTM showed no change in Sema3A mRNA expression." (PMID 35654941, 2022).
proliferative diabetic retinopathy (2 papers, 2021 to 2022). Advanced retinopathy due to diabetes mellitus characterized by the formation of new vessels in the retina. "BI-X is an intravitreal anti-Sema3A agent under clinical investigation in patients with proliferative diabetic retinopathy (PDR) and diabetic macular ischemia (DMI)." (PMID 35727188, 2022).
spinal cord injury (2 papers, 2023 to 2024). Penetrating and non-penetrating injuries to the spinal cord resulting from traumatic external forces (e.g., WOUNDS, GUNSHOT; WHIPLASH INJURIES; etc.). "Semaphorin 3A (Sema3A) was described to prevent axonal regeneration through binding to the NRP1/PlexinA4 receptor complex after spinal cord injury (SCI)." (PMID 37898403, 2023).
type 1 diabetes (2 papers, 2016 to 2025). "Whereas SEMA3A is not highly expressed in the healthy retina of adult mice, SEMA3A expression is upregulated in a mouse model of type 1 diabetes induced by streptozotocin treatment, mostly via secretion from RGCs." (PMID 26923176, 2016).
viral myocarditis (2 papers, 2017 to 2025). Myocarditis that is caused by an infection with a viral agent. "In the setting of viral myocarditis, semaphorin-3A (SEMA3A), a secreted signaling molecule involved in cell migration, growth, and survival, plays a protective role in cardiomyocyte maintenance." (PMID 40705152, 2025). "A similar increase in inflammation was seen in Sema3A HZ mice compared to WT when using the non-sterile model for cardiac injury of Coxsackie B3 induced viral myocarditis, where Sema3A expression could also be found on macrophages." (PMID 28540528, 2017).
acromelic dysplasia (1 paper, 2021). "Interestingly, also SEMA3A mutations may cause short stature, as can be observed in FBN1 mutation patients with acromelic dysplasias." (PMID 34895303, 2021).
acute respiratory distress syndrome (1 paper, 2025). Progressive and life-threatening pulmonary distress in the absence of an underlying pulmonary condition, usually following major trauma or surgery. "Expression of SEMA3A inactivates the ERK/JNK pathway, which reduces inflammation during acute respiratory distress syndrome." (PMID 40725399, 2025).
allergic asthma (1 paper, 2016). A asthma with a basis in a pathological type I hypersensitivity reaction. "It suggests that Sema3A could be considered to modulate, not only ASM hyperplasia but also, airway inflammation in allergic asthma." (PMID 27791986, 2016).
anorectal malformation (1 paper, 2020). "Comparison of the ganglionic colon of HSCR patients to the colon of patients with anorectal malformation shows reduced expression of the synaptic molecule synapsin 1 in HSCR, which is inversely correlated with Sema3A expression." (PMID 32934297, 2020).
autism spectrum disorder (1 paper, 2023). A spectrum of developmental disorders that includes autism, and Asperger syndrome. "Existing evidence indicates that SEMA3A alleles are associated with genetic disorders in the central nervous system, including autism spectrum disorders and neuronal migration." (PMID 38111702, 2023).
autonomic dysreflexia (1 paper, 2016). A syndrome associated with damage to the spinal cord above the mid thoracic level (see SPINAL CORD INJURIES) characterized by a marked increase in the sympathetic response to minor stimuli such as bladder or rectal distention. "Finally, inhibition from Sema3A on axon outgrowth of calcitonin gene related peptide- (CGRP-) positive sensory fibers is shown following injection of adenovirus encoding Sema3A in the spinal cord after complete spinal transection in a model of autonomic dysreflexia." (PMID 27057361, 2016).
bacterial pneumonia (1 paper, 2025). Acute infection of the lung parenchyma caused by bacteria (e.g., Streptococcus pneumoniae, Haemophilus influenzae, Chlamydia pneumoniae, Mycoplasma pneumoniae, and Legionella pneumophila). "SEMA3A significantly decreased in MASLD bacterial pneumonia (Δ = 1.8, 95% CI 0.5–3.1), and non-MASLD influenza group (Δ = 7.3, 95% CI 5.9–8.7)." (PMID 40869413, 2025).
bladder cancer (1 paper, 2024). "The authors also examined sema3A in tissue and found high expression in high-grade bladder cancer, moderate expression in low-grade, and hardly any expression in non-malignant tissues." (PMID 39061999, 2024). "Yet, with regard to bladder cancer, only the role of semaphorin 3A and 4D has been studied." (PMID 39061999, 2024).
bone tumor (1 paper, 2023). "Sema3A signaling plays a pivotal role in bone tumor progression, and its effects are multifaceted." (PMID 38078001, 2023).
cardiac ischemia (1 paper, 2017). "In mice, the expression of Sema3A also increases in response to myocardial ischemia being expressed by infiltrating leukocytes." (PMID 28540528, 2017). "Despite cardiac ischemia initiating changes in vascular permeability and angiogenesis, the reduced Sema3A in the HZ mice did not affect these processes." (PMID 28540528, 2017).
chondrodysplasia (1 paper, 2024). "Osteoblast-derived semaphorin3A (Sema3A) has been reported to be involved in bone protection, and Sema3A knockout mice have been reported to exhibit chondrodysplasia." (PMID 38727898, 2024).
choroidal neovascularization (1 paper, 2021). An eye disorder described by the growth of new blood vessels that originate from the choroid through a break in the Bruch membrane into the sub–retinal pigment epithelium (sub-RPE) or subretinal space. "Here, we provide evidence that ligands for neuropilin‐1 (NRP1), such as Semaphorin 3A and VEGF‐A, are elevated in the vitreous of patients with AMD at times of active choroidal neovascularization (CNV)." (PMID 33876574, 2021).
chronic hepatitis C infection (1 paper, 2024). "Semaphorins were reported as potential biomarkers for the severity of chronic hepatitis C infection, and SEMA3A and SEMA6D correlated with the fibrosis stage." (PMID 39770766, 2024).
chronic myelogenous leukemia (1 paper, 2019). "The expression of the secreted semaphorin SEMA3A was reported to be lower in acute lymphoid and myeloid leukemia (ALL/AML) and chronic myelogenous leukemia (CML) cells, compared to hematopoietic cells found in the normal BM." (PMID 31143707, 2019).
chronic tonsillitis (1 paper, 2020). "SEMA3A was significantly downregulated in OPC compared with chronic tonsillitis tissues (p = 0.005)." (PMID 32842711, 2020). "A reduction in SEMA3A expression was observed in our OPC samples compared with chronic tonsillitis tissues." (PMID 32842711, 2020). "Only 3 of 17 (17.64%) chronic tonsillitis tissues showed low SEMA3A expression, whereas 19 of 32 (59.37%) specimens of OPC tissue displayed low SEMA3A expression, indicating that SEMA3A expression was significantly upregulated in the OPC tissues compared with chronic tonsillitis tissues (p = 0.005)." (PMID 32842711, 2020).
clear cell renal cell carcinoma (1 paper, 2024). "Examining a clear cell renal cell carcinoma patient cohort, we find that SEMA3A expression is associated with reduced survival, and that T-cells appear trapped in SEMA3A rich regions." (PMID 38609390, 2024). "Analysis of publicly available TCGA data revealed that high SEMA3A expression was associated with poorer survival in clear cell renal cell carcinoma (ccRCC), while another Semaphorin, SEMA4A was not." (PMID 38609390, 2024). "In clear cell renal cell carcinoma (ccRCC) patients we find that NRP1+ T cells often express PD-1 and are trapped in SEMA3A-rich areas." (PMID 38609390, 2024).
colitis (1 paper, 2025). Inflammation of the colon. "With respect to T-cell activation and differentiation, Sema3A was shown to inhibit T-cell proliferation and to reduce the production of pro-inflammatory cytokines in immune-mediated diseases such as RA and colitis." (PMID 41303643, 2025).
congenital heart defects (1 paper, 2021). "Moreover, SEMA3A and PRRX2 mutations also lead to congenital heart defects." (PMID 34895303, 2021).
Crohn disease (1 paper, 2015). A gastrointestinal disorder characterized by chronic inflammation involving all layers of the intestinal wall, noncaseating granulomas affecting the intestinal wall and regional lymph nodes, and transmural fibrosis. "We aim to assess the possible involvement of semaphorin3A (sema3A) and 4A (sema4A) in peripheral immune responses and bowel tissue inflammation of patients suffering from Crohn’s disease (CD) and ulcerative colitis (UC)." (PMID 25978359, 2015).
diverticulitis (1 paper, 2015). An infection that develops in the diverticula of the intestinal tract. "We analyzed the expression pattern of the immune semaphorins—namely, sema3A and sema4A in colon biopsies taken from all IBD patients at onset of disease, from patients suffering from diverticulitis and from normal controls." (PMID 25978359, 2015).